CAV1 (caveolin 1)
Diseases named in the same sentence as CAV1 in open-access papers (continued):
Sharing a sentence is not in itself a finding about the gene and the disease.
cancer (continued). "In this perspective, since the recent growing body of literature indicating a cooperation between Cav-1 and the polymerase transcription released factor PTRF/Cavin-1 in cancer progression, it will be certainly important to assess their relative contribution in RMS malignancy." (PMID 24427291, 2014). "Although we proved the interaction between BKCa and caveolin-1 in MCF-7 cells, whether our findings can be extended to other cancer cell contexts is yet to be verified." (PMID 25397596, 2014). "By contrast, breast, ovarian, hepatic and lung cancer exhibit an upregulation of Cav-1 in cancer cells compared with the non-cancerous tissues." (PMID 25202343, 2014). "The caveolin-1 gene (CAV1) consists of three exons and localizes to the D7S522 locus in the q31.1 region of human chromosome 7, a known fragile site (FRA7G) that is frequently deleted in human cancer." (PMID 25397596, 2014). "An exosome mechanism for TARS secretion would be consistent with other signaling proteins that regulate the extracellular matrix and are overexpressed in cancer including heat shock protein 90 (HSP90), plasminogen activator inhibitor-1 (PAI-1) and caveolin-1 (cav-1)." (PMID 25163878, 2014). "Stromal cells lacking Cav1 undergo aerobic glycolysis and secrete energy-rich metabolites that directly feed cancer cells and fuel mitochondrial respiration of adjacent cells through the phenomenon called the ‘reverse Warburg effect’." (PMID 23521716, 2013). "In those settings Cav1 appears to be downregulated and seems to play a negative role in cancer transformation." (PMID 23521716, 2013). "Unlike in cancer progression we show that an increase in Cav-1 and Vegf expression is negatively correlated with Foxm1 expression." (PMID 24391823, 2013). "Cav1 has only been reported in invadopodia in three cell lines; that is, the nonphosphorylated form in two cancer cell lines, and the phosphorylated form in an ACTH-stimulated adrenal cell line." (PMID 22873355, 2012). "In the non-IBC tissues, 48.2% of patient tissue samples revealed negative staining for cav-1 in carcinoma cells, whereas 29.6% scored +, 7.4% scored ++ and 14.8% scored +++." (PMID 21199580, 2011). "Preliminary experiments excluded the possibility that the CAV1-mediated activity of RES was due to direct CAV1-dependent activation of ERα and ERβ and proposed a novel mechanism responsible for RES-CAV1 mediated anti-cancer activity in HCC." (PMID 19321006, 2009). "Histologically non-neoplastic ductal epithelium adjacent to cancer cells showed little or no immunoreactivity with caveolin-1." (PMID 12402154, 2002). "It is therefore suggested that the function of caveolin-1 is not uniform in carcinoma, depending on the origin of the carcinoma and on the expression status of various growth factors and hormones." (PMID 11953823, 2002). "CAV1 inhibition reduced expression of dormancy regulators E-cadherin, RAC1 and p21, enhanced cancer stemness markers, and disrupted downstream STAT3/P70S6K and AMPKα signalling pathways, prompting cancer cells to exit from dormancy and initiate autophagy-induced cell death." (PMID 40715090, 2025). "Prior research has demonstrated that CAV1 levels rise significantly in confluent fibroblasts, a trend which we observed as localized staining in areas of cell–cell contact within the fibroblast cells but not within the cancer cells." (PMID 40385530, 2025). "Thus, although previous studies have suggested that the expressions of DNM2 and CAV1 affect cancer cell invasion and metastasis, to our knowledge, no study has evaluated the clinicopathological effects of these protein expressions in OSCC." (PMID 40419438, 2025). "In addition, aligned fibers and Cav-1 dependent stability of the actin cytoskeleton coordinately maintain the nuclear accumulation of YAP and promote FAs formation and cytoskeletal integrity to guide cancer cell migration." (PMID 39318372, 2024).
cancer (continued). "Hence, the classification effectiveness of ten biomarkers which was assessed overall was based on GPX2 and GPX3 as factors from the enriched pathways and CAV1, ENO1, NQO1, and P4HB as factors from functional classes to determine whether a patient had cancer." (PMID 37955007, 2023). "The cellular prion protein PrPC partners with caveolin-1 (CAV1) in neurodegenerative diseases but whether this interplay occurs in cancer has never been investigated." (PMID 35962130, 2022). "But so far, there are no studies on the effect of CAV-1/LOX-1 on cancer development." (PMID 33935779, 2021). "It has been confirmed that remodeling of the ECM by CAV1 is important for the architecture of normal organs, especially those that are rich in ECM fibers, and fibroblast expression of CAV1 favors directional migration and invasiveness of carcinoma cells in vitro." (PMID 33870858, 2021). "Importantly, the authors demonstrated that cancer cells promoted NF-κΒ and HIF-1 activation in adjacent fibroblasts in a paracrine manner, and that the pharmacological inactivation of both HIF-1 and NF-κΒ prevented Cav-1 degradation." (PMID 32231206, 2020). "CAV1 phosphorylation on Y14 is essential to promote migration/invasion and metastatic cells have elevated levels of CAV1 pY14 in comparison to non-metastatic cancer cells." (PMID 32152405, 2020). "Thus, we will also elaborate on how CAV1 participates in intracellular communication between organelles as well as signaling between cells (non-canonical pathways) in cancer." (PMID 32458269, 2020). "However, the precise function of CAV1 at these sites often still remains to be defined, as does the role of these pools in processes related to the development of cancer (non-canonical roles)." (PMID 32458269, 2020). "To explore whether regulation of CAVIN1 and CAV1 expression by YAP/TAZ-TEAD is a general phenomenon, we used data from cancer cell line encyclopedia (CCLE) and conducted pairwise bioinformatic analysis of CYR61 and CTGF, CAVIN1, or CAV1 expression, respectively." (PMID 30595521, 2019). "During the course of these experiments, we determined that A431 cells (similar to several other commonly cancer cell lines such as HeLa cells) do not express Cavin2 but have significant expression of the universal components of caveolae, Cavin1, CAV1, and Cavin3." (PMID 31332168, 2019). "While CAV1 depletion resulted in a slight increase in cell-surface HER2, a more pronounced effect of knocking down CAV1 was demonstrated by the extended half-life (P < 0.05, Student’s t-test) of HER2 at the cell membrane in NCIN87, UMUC14, and BT474 cancer cells." (PMID 30510281, 2018). "Therefore exposure of cancer cells to anti-neoplastic drugs at non-lethal drug concentrations induces signaling events and changes in transcription that favor CAV1-dependent migration, invasion and metastasis." (PMID 29340103, 2017). "While Cav1 deletion in KO→WT chimeras positively affected metastatic cancer cell growth at a late stage, their extravasation and lodging in the early stage after intravenous cancer cell injection was not affected." (PMID 29212030, 2017). "So the question of whether or not Cav-1/MT1-MMP are co-located at invadopodia might have important implications with regard to the mechanisms involved in the regulation of cancer cell invasion." (PMID 26919102, 2016). "Cav-1 RNA expression was highest in non-malignant tissue and decreased during cancer progression." (PMID 27764093, 2016).
cancer (continued). "Cav-1 expression was highest in non-malignant tissue and decreased during cancer progression." (PMID 27764093, 2016). "This suggests that recruitment of Cav1 to caveolae may alter the relationship between non-caveolar Cav1 and Gal3 that is critical to their coordinated regulation of FA dynamics and cancer cell migration." (PMID 25942420, 2015). "Since not all normal cells express Cav-1 and not all cells with low/no Cav-1 expression are primary cancer cells, Cav-1 might be just one of critical molecules responsible for assisting cells defending harmful stress." (PMID 26431273, 2015). "Studies suggest that Cav-1 is a chemotherapy-response gene independent of cancer type." (PMID 26431273, 2015). "Furthermore, the molecular mechanisms of caveolin-1 in cancer progression have not been fully elucidated, although it likely involves modulation of lipid rafts and, based on the present data, IQGAP1." (PMID 25924234, 2015). "In 45 cancer specimens, 6 (13.3%) patients showed high levels of stromal Cav-1 staining, whereas 8 (17.8%) showed a lower intermediate level of staining, and 31 (68.9%) showed an absence of stromal Cav-1 staining." (PMID 24949874, 2014). "In addition, pancreatic, esophagus, renal and oral cancer have shown the downregulation of Cav-1 in cancer cells compared with non-cancerous tissues." (PMID 25202343, 2014). "The role played by Cav1 in cancer and progression has not been fully clarified." (PMID 23521716, 2013). "In addition, although Cav1 plays a role in several oncogenic pathways, Cav1 null mice do not present a higher incidence of carcinomas." (PMID 23521716, 2013). "The mRNA expression of an array of heterotypic biomarkers may explain the course of this patient's clinical outcome as gene expression indicates the participation of unique cancer-related transcripts specifically related to GBM stem cells, such as caveolin-1 and −2." (PMID 22995409, 2012). "Caveolin-1 (Cav-1) is the major coat protein of caveolae, regulating the activity of signalling molecules in cancer, and can make both a negative and positive impact on cancer progression." (PMID 22353809, 2012). "The majority of the cells in cancer or non-cancerous cases, including fibroblasts, type I pneumocytes, bronchial epithelium and smooth muscle cells, showed positive staining for cav-1." (PMID 22200856, 2012). "Cav-1 expression can have both a positive and negative effect on cancer progression." (PMID 22353809, 2012). "Furthermore, there was a difference between IBC and non-IBC carcinoma cells in regard to co-expression of cathepsin B and caveolin-1." (PMID 22093547, 2011). "However, the ability of CAV1 to regulate survivin expression and cell proliferation is severely impaired in metastasic cancer cells lacking E-cadherin." (PMID 18694510, 2008). "Based on this observation, they suggest that where cancer cells express caveolin-1, they may have been positively selected due to its negative regulatory effects on apoptosis." (PMID 18949068, 2007). "However, we observed that neither S387A substitution, dephosphorylation mimic, or S387E substitution, phosphorylation mimic, of Ago2, altered Ago2/CAV1 interaction (Fig. EV1H), supporting that Ago2/CAV1 interaction is not responsible for Ago2 association with endosomes in cancer cells." (PMID 38649663, 2024). "Furthermore, CAV1 methylation detected cancer in false negative biopsies (AUC 0.70)." (PMID 36036057, 2023). "Moreover, CAV1 was a differentiating gene regardless of cancer grade." (PMID 37233761, 2023). "Bearing in mind that the reprogramming of energy metabolism is required in cancer cells to meet both the bioenergetic and biosynthetic needs to sustain increased proliferation, migration, and invasion, we evaluated the metabolism of metastatic cells expressing or not CAV1." (PMID 35740528, 2022).
cancer (continued). "In addition, Faber and colleagues reported that, although CAV1 is not essential for peroxisome biogenesis, peroxisomal CAV1 is involved in hepatocyte proliferation and lipid metabolism, and aberrant expression of the protein could promote cancer development." (PMID 32458269, 2020). "It was demonstrated that Cav-1 is not expressed in the epithelial compartment in normal gastric mucosa and in the metaplastic intestinal epithelium while its expression is significantly higher in advanced versus early cancers and an independent prognostic factor of poor survival." (PMID 29141593, 2017). "However, it is not clear whether the caveolin-1 (CAV1)-mediated JNK/Foxo3a pathway is involved in cancer cell apoptosis." (PMID 28099944, 2017). "Whether CAV1 influences such a crucial switch in cancer is not yet reported." (PMID 27852311, 2016). "As long non-coding RNA signatures have been previously shown to be predictive in cancer, we chose to investigate whether this long non-coding RNA harbored any potential interactions with CAV1, given that CAV1 was the basis upon which sample stratification was conducted." (PMID 26566034, 2015). "Similarly, using flow cytometry, we demonstrate that raft-dependent endocytosis of AMF/PGI is increased in metastatic HT29 cancer cells expressing low levels of caveolin-1 relative to metastatic, caveolin-1-expressing, HCT116 colon cells and non-metastatic Caco-2 cells." (PMID 18974847, 2008). "High expression of ITGB1, CAV1 and low expression of CRYBA1, CEACAM5 were observed in all, suggesting the lack of anchorage-independent growth of the two cancer-derived cells is due to different mechanisms than lack of anoikis resistance." (PMID 37264224, 2023). "However, on the other hand, expression of CAV1 in cancer cells lacking E-cadherin, which is lost in cancer development during the epithelial to mesenchymal transition, enhances the metastatic potential by a pathway involving CAV1 phosphorylation on Y14 and activation of the Rab5-Rac1 signaling axis." (PMID 35740528, 2022). "Because the ability to migrate and permeate the extracellular matrix are important events in cancer metastasis, we then evaluated the effect of 4β-TPA-mediated up-regulation of CAV1 in transmigration assays in the absence of serum." (PMID 26054531, 2015). "Expression of unique cancer-related transcripts in these CD133-positive cells, such as caveolin-1 and −2, do not appear to have been previously reported in the literature." (PMID 22995409, 2012). "The typical caveolin-1 (CAV1) protein is a principal component of the caveolin family and its reduced or absent expression was shown in most human cancer cells." (PMID 19321006, 2009). "As shown, the obvious decrease of Caveolin-1 did not decrease the internalization of exosomes in mutEGFR cancer cells, while knockdown of Clathrin contributed to a significant decrease of PKH-67-labeled cancer cells indicated by flow cytometry." (PMID 33461557, 2021). "However, although AT2R activation leads to dephosphorylation of many AT1R effector molecules, CAV1 as a target of AT2R signaling, and the possible consequences thereof in the context of cancer, have not been described." (PMID 31484460, 2019). "However, in previous gene expression profiling studies, CAV1 and CAV2 were shown to be expressed at higher levels in normal breast-like cancer." (PMID 18612310, 2008). "Interestingly, unlike CAV1, the level of CAV2 mRNA was also increased in the majority of basal-like cancer." (PMID 18612310, 2008). "Immunohistochemical assays showed that the expression of both caveolins was more abundant in the myoepithelial cells of the mammary duct than ductal epithelial cell in normal breast tissues, while fewer expressions of CAV1 and CAV2 proteins were detected in cancer tissues (data not shown)." (PMID 15305200, 2004).
cancer (continued). "pCav1 increases membrane lipid order in FAs and promotes FAK stabilization within FAs in multiple cancer cell lines including the PC3 PCa cell line, a cell line that expresses no endogenous PTRF and thus no caveolae, suggestive of a role for non-caveolar Cav1 scaffolds." (PMID 25942420, 2015).
infection (114 papers, 2004 to 2026). The state of being infected such as from the introduction of a foreign agent such as serum, vaccine, antigenic substance or organism. "Although Cav-1-deficient mice had increased production of inflammatory signals, including chemokines and nitric oxide, they still suffered from a more severe infection and lower survival rates." (PMID 39791703, 2024). "In the HUVEC, the blockage of ITGB1 with antibody and inhibition of CAV-1 with filipin or depletion of ITGB1 and CAV-1 encoding genes with siRNA interference caused the noticeable decrease of intracellular leptospires during infection." (PMID 36137081, 2022). "As EMCV-VP1 co-localized with caveolin-1 at 120 min post infection, we next investigated caveolin-1 association with EMCV internalization." (PMID 33761945, 2021). "To determine if raft formation was impaired during persistent hPIV1 infection, we quantitated raft association of cellular raft marker protein, caveolin-1." (PMID 34529742, 2021). "First, urban areas are linked with a higher dog density and thus with a higher natural exposure risk because dogs can shed CAV-1 in their urine after infection for at least 6 months or they can shed CAV-2 after infection or even after MLV vaccination." (PMID 33096809, 2020). "Given that several interventions that inhibit PM repair also inhibit T. cruzi invasion, we examined the impact of EndoA2 depletion on the susceptibility of WT and Cav1 KO MEFs to infection by these parasites." (PMID 33093240, 2020). "We first exposed both cell types to infective stages of T. cruzi for increasing periods of time and found that Cav1 KO MEFs were slightly less susceptible than WT MEFs to infection." (PMID 33093240, 2020). "The consistent association of NS3 with Cav-1 at different times post infection suggests the involvement of lipid rafts in the late steps of infection." (PMID 24643062, 2014). "In vivo knockdown studies showed that disruption of the IFN response by cav-1 depletion renders the host more susceptible to infection." (PMID 23874753, 2013). "Recent reports on Cav1-deficient mice revealed a general enhanced susceptibility to disease provoked by local or systemic infection through certain pathogens including bacteria (Salmonella typhimurium, Pseudomonas aeruginosa) or parasites (Trypanosoma cruzi)." (PMID 23592983, 2013). "Quantification of this association determined that at early time points during infection, ∼60% of the CCVs colocalized with both caveolin-1-GFP and flotillin-1-GFP." (PMID 18225954, 2008). "CAV1-deficient mice are in a low-grade pro-inflammatory state, particularly sensitive to infection." (PMID 41155280, 2025). "Interestingly, Cav–1 KO mice were more susceptible to death after infection with Salmonella enterica sv." (PMID 35911737, 2022). "In particular, only the inhibition of ITGB1 in the THP-1 or blockage of both the ITGB1 and CAV-1 in HUVEC could cause the significant decrease of intracellular leptospires during infection." (PMID 36137081, 2022). "Infection of influenza A virus (IVA) is also associated with CAV-1-mediated signal transduction." (PMID 32357558, 2020). "Importantly, deficiency in Cav-1 significantly delayed alphavirus neuroinvasion during early infection, highlighting the important role of caveolae in CNS entry." (PMID 32047126, 2020). "Therefore, it may be worthwhile to investigate age-related defects in innate defenses against pathogen infection in association with the expression of CAV1 and ZNRF1." (PMID 28593998, 2017). "Pharmacological blockade of caveola-mediated endocytosis (CavME) with nystatin or genetic silencing of caveolin-1 (CAV1) similarly impaired infection, indicating that ASFV entry into its target cells is CavME dependent." (PMID 42112906, 2026). "Cav-1 KO mice had decreased viral titers in the brain as compared to WT mice during early timepoints following peripheral infection, suggesting that Cav-1 plays an important role in WEEV neuroinvasion." (PMID 40005568, 2025).